HMGB1 (high mobility group box 1)
Diseases named in the same sentence as HMGB1 in open-access papers (continued):
Sharing a sentence is not in itself a finding about the gene and the disease.
lung squamous cell carcinoma (7 papers, 2016 to 2023). "After that, we scrutinized the Lung Squamous Cell Carcinoma (TCGA, Provisional) dataset for changes in expression of HMGB1 and observed 148 cases in which HMGB1 was over-expressed out of 504 cases (24%)." (PMID 26840258, 2016).
Pain (7 papers, 2014 to 2024). An unpleasant sensory and emotional experience associated with actual or potential tissue damage, or described in terms of such damage. "The mechanism of this function depended on the process: pCaMKIV localized in the nuclei of DRG neurons and regulated HMGB1 which was an important mediator of neuropathic pain." (PMID 27216039, 2016). "HMGB1 neuronal signalling in neuropathic pain may be dependent on either of two receptors for TLR4 and/or advanced glycation end products (RAGE)." (PMID 25120576, 2014). "More studies are required to confirm whether Tan IIA produces protective effects to alleviate hyperpathia in SNL-induced neuropathic pain, and whether Tan IIA downregulates HMGB1 and TLR4 expression in the spinal cord is not yet clear." (PMID 25120576, 2014).
polycystic ovary syndrome (7 papers, 2015 to 2025). A disorder that manifests as multiple cysts on the ovaries. "In the context of the ovary, HMGB1 has been linked to polycystic ovary syndrome, chronic inflammation, and miscarriage." (PMID 41009742, 2025). "It was shown that HMGB1 is implicated in placental inflammation, endometriosis, and polycystic ovarian syndrome (PCOS)." (PMID 41009742, 2025). "CRY may prevent ovarian tissue damage caused by polycystic ovary syndrome through the regulating the expression and function of HMGB1, TLR4, and NF-κB." (PMID 41301950, 2025).
polymyositis (7 papers, 2013 to 2023). A rare idiopathic inflammatory myopathy characterized by symmetric proximal muscle weakness and elevated muscle enzymes. "Anti-HMGB1 antibodies have been described in sera of patients with septic shock, polymyositis, dermatomyositis and in active SLE." (PMID 24007972, 2013). "For example, in polymyositis, the expression levels of miR-381-3p are lessened in patients with polymyositis, and miR-381-3p reduces inflammation and macrophage infiltration in polymyositis by down-regulating HMGB1." (PMID 34784841, 2021). "The research on murine model of polymyositis, a subtype of IIM, revealed that the inhibition of necroptosis or HMGB1, one of major DAMPs released from muscle fibers undergoing necroptosis, ameliorated muscle inflammation and recovered muscle weakness." (PMID 37483632, 2023). "HMGB1 has been widely reported as a central role in the pathogenesis of many CTD, such as SLE, polymyositis or dermatomyositis with ILD, and RA." (PMID 32393322, 2020). "For instance, increased levels of S-100B (one RAGE ligand) and RAGE are observed in experimental animal models of myasthenia gravis; and overexpression of HMGB1, CML(both RAGE ligands), and RAGE was found in the muscle fibers of polymyositis and dermatomyositis patients." (PMID 34620111, 2021).
respiratory failure (7 papers, 2016 to 2023). The significant impairment of gas exchange within the lungs resulting in hypoxia, hypercarbia, or both, to the extent that organ tissue perfusion is severely compromised. "Theoretically, PMX adsorbs inflammatory mediators, such as high mobility group box 1, neutrophils and interleukin-6 that cause respiratory failure in AE-IPF." (PMID 37821999, 2023). "The present study showed that the combination of a high sputum HMGB1 level and a high sputum lytA DNA load was associated with inflammation (IL-8 elevation) and respiratory failure (reduced PaO2/FiO2 ratio) in patients with pneumococcal CAP." (PMID 30194360, 2018). "In pneumococcal pneumonia, high sputum lytA DNA load was associated with respiratory failure (low PaO2/FiO2 ratio; p = 0.019), and high sputum HMGB1 level was associated with bacteraemia (p = 0.006)." (PMID 30194360, 2018). "Extracellular HMGB1 would mediate deleterious pulmonary inflammatory responses, such as epithelial barrier derangement, neutrophil infiltration, lung edema and injury, which subsequently cause respiratory failure, and even death." (PMID 27634894, 2016). "Patients with respiratory failure showed trend of increase in HMGB1 [plasma concentration, median(IQR), 3.5(2.1–5.2) vs 3.2(1.7–4.5); 10th–90th percentile, 1.6–13.5 vs 1.0–6.0 ng/mL; gene expression RQ, 1.4(0.9–3.1) vs 1.0(0.6–3.0)]." (PMID 27434276, 2016). "Plasma IL-8/CXCL8 (adjusted OR 1.12, 95%CI 1.02–1.23 per unit increase, P = 0.021) and HMGB1 (adjusted OR 1.42 per unit increase, 95%CI 1.08–1.87, P = 0.012) concentrations were independent predictors for respiratory failure, as well as for ICU admission/death." (PMID 27434276, 2016). "However, when doing separate analyses of DAMP and PAMP, we found that respiratory failure was driven by the lytA DNA load, and the PaO2/FiO2 ratio was not at all related to the HMGB1 level in univariate analysis." (PMID 30194360, 2018).
allergic asthma (6 papers, 2017 to 2025). A asthma with a basis in a pathological type I hypersensitivity reaction. "Intriguingly, RAGE deficiency or HMGB1 neutralisation ameliorates type-2 inflammation in preclinical models of allergic asthma." (PMID 28099113, 2017). "There is scarce information from the relationship of these proteins and treatments, but it recently has been demonstrated in an allergic asthma rat model the role of AIT inhibiting the HMGB1/TLR4/NF-κB signaling, in agreement with our data." (PMID 40650018, 2025). "In a mouse model of allergic asthma using the house dust mite, increased HMGB1 expression was seen in the airways." (PMID 41303221, 2025). "In preclinical models of allergic asthma, anti-HMGB1 or genetic ablation of RAGE (receptor for advanced glycation endproducts), one of the receptors ligated by HMGB1, is protective." (PMID 32658914, 2020). "Similarly, we previously identified that HMGB1 was common to the pathogenesis of house dust mite- and cockroach-induced allergic asthma in mice." (PMID 28099113, 2017). "Studies have shown that HMGB1 can influence CD4+ T cell differentiation, mediating inflammatory responses in conditions of allergic asthma." (PMID 40842957, 2025). "Data obtained and collected in this review indicate that HMGB1 is a potential therapeutic target of allergic asthma, nevertheless it is difficult to detect its levels, because it is a nuclear protein." (PMID 28630596, 2017).
ANCA-associated vasculitis (6 papers, 2012 to 2023). "In a recent study by Bruchfeld and colleagues, increased serum levels and renal tissue expression of HMGB1 were demonstrated in ANCA-associated vasculitis with renal involvement." (PMID 22348591, 2012). "This was in line with the result of migration assay, indicating that HMGB1 could enhance the interaction between endothelium and neutrophils in ANCA‐associated vasculitis, to some degree, by promoting IL‐8 production." (PMID 28181422, 2017). "Recent studies found that the circulating high-mobility group box 1 (HMGB1) levels could reflect the disease activity of antineutrophil cytoplasmic antibody (ANCA)-associated vasculitis (AAV)." (PMID 26739852, 2016).
biliary atresia (6 papers, 2022 to 2025). A rare, biliary tract disease characterized by progressive obliterative cholangiopathy of the intra- and extrahepatic bile ducts, occurring in the embryonic/ perinatal period, leading to severe and persistent neonatal jaundice and acholic stool. "Serum HMGB1 levels at 30 min after reperfusion were positively associated with early PARDS among pediatric patients with biliary atresia who had undergone LDLT." (PMID 36944948, 2023). "Our Chinese study indicated that serum HMGB1 levels 30 min after reperfusion were positively associated with LDLT-induced PARDS in children with biliary atresia." (PMID 36944948, 2023). "Additionally, HMGB1 has been shown to be an important marker for biliary atresia, and to also have a likely pathogenic role in this setting as anti-HMGB1 treatment increased survival in a murine biliary atresia model." (PMID 37636574, 2023). "In this study, we conducted a detailed evaluation of the association between intraoperative HMGB1 elevation and PARDS during the first week after LDLT in children with biliary atresia in China." (PMID 36944948, 2023). "In a recent study, HMGB1 released by cholangiocytes was involved in the pathogenesis of biliary atresia and correlated with an increase in afflicted children." (PMID 36944948, 2023). "It has been reported that HBD2 ranges with age, and serum HMGB-1 also increases in other neonatal diseases, such as persistent pulmonary hypertension, hypoxic-ischemic encephalopathy and biliary atresia." (PMID 36147817, 2022). "We evaluated the link between anomalies of intraoperative serum HMGB1 and PARDS in pediatric LDLT recipients with biliary atresia during the first week after transplant." (PMID 36944948, 2023). "In conclusion, there is a positive relationship between serum HMGB1 levels 30 min after reperfusion and PARDS during the first week after LDLT in children with biliary atresia in China." (PMID 36944948, 2023). "For example, a previous study reported that high-mobility group box-1 (HMGB-1) up-regulated the levels of TLR-2/4, which belongs to the group of classical PRRs, on murine NK cells, leading to their activation in rotavirus-induced murine biliary atresia." (PMID 36776839, 2023). "In addition, limited research has demonstrated the relationship between HMGB1 and PARDS after LDLT in children with biliary atresia." (PMID 36944948, 2023). "Compared with other studies of lung injury following liver transplantation, our study was conducted in children with biliary atresia who had undergone LDLT, and dynamic changes in serum HMGB1 levels may reflect minor alterations in distal organ inflammatory responses." (PMID 36944948, 2023).
chorioamnionitis (6 papers, 2016 to 2022). A morphologic finding indicating inflammation of the fetal sac membranes. "These date implicated HMGB1 as a novel candidate biomarker for the early prediction of preterm birth determined by chorioamnionitis." (PMID 31875024, 2019). "HMGB1 is implicated in pregnancy complications, such as preterm birth and chorioamnionitis." (PMID 26851389, 2016). "The significant increase of the amniotic fluid HMGB1 concentration and a decreased amniotic fluid sRAGE in our experiment concur with findings observed in chorioamnionitis in women at term delivery." (PMID 34439812, 2021). "This study was conducted to compare the levels of HMGB1 in amniotic fluid and amnion membranes in women with chorioamnionitis/intra-amniotic inflammation to the levels in healthy controls." (PMID 31875024, 2019). "The levels of HMGB1 in amniotic fluid and amnion membranes were significantly higher in patients with intra-amniotic inflammation/chorioamnionitis than in those without inflammation." (PMID 31875024, 2019).
chronic heart failure (6 papers, 2013 to 2026). "Upregulation of HMGB1 and downregulation of miRNA-129-5p was observed in patients with chronic heart failure." (PMID 36499336, 2022).
encephalitis (6 papers, 2017 to 2023). An acute inflammatory process affecting the brain parenchyma. "High level of HMGB1, IL-6, and IL-17A has been detected in CSF of patients with an anti-NMDA receptor (NMDAR) encephalitis (neuroinflammatory disorder), reflecting the underlying neuroinflammatory processes but does not report any precise role of HMGB1 in disease pathology." (PMID 30271319, 2018). "However, the functions of extracellular HMGB1 need to be further investigated in the toxoplasmosis, maybe especially in the encephalitis." (PMID 28484433, 2017).
fibrosarcoma (6 papers, 2018 to 2023). A malignant mesenchymal fibroblastic neoplasm affecting the soft tissue and bone. "During chemotherapy or radiotherapy, HMGB1 released by dying MCA205 fibrosarcoma cells activated tumor antigen-specific T-cell immunity through acting on TLR4 expressed by antigen presenting cells." (PMID 34257571, 2021). "HMGB1-RAGE signals have been reported to exacerbate the malignant phenotype of HT1080 human fibrosarcoma cell lines." (PMID 34257571, 2021). "DACT also stimulated all ICD hallmarks (eIF2α phosphorylation, CALR exposure, ATP and HMGB1 release, as well as induction of type 1 interferon‐related metagene) in another cell line, the murine methylcholanthrene‐induced fibrosarcoma MCA205 (Fig EV1)." (PMID 32323922, 2020). "Blocking the binding of HMGB1 to RAGE by expressing the HMGB1 150–183 peptide (COOH-terminal motif) inhibits invasive migration of fibrosarcoma cells." (PMID 29636841, 2018). "There have been several studies on the role of HMGB1 in fibrosarcoma cells in vitro." (PMID 34257571, 2021). "Using RAGE- or dominant-negative RAGE-expressing HT1080 human fibrosarcoma cells, papaverine suppressed RAGE-dependent HT1080 human fibrosarcoma cell proliferation, migration, and invasion in a dose-dependent manner through a significant inhibition of RAGE-dependent NF-κB driven by HMGB1." (PMID 32443845, 2020).
interstitial lung disease (6 papers, 2016 to 2022). A diverse group of lung diseases that affect the lung parenchyma. "In patients with inflammatory myopathies, the serum levels of HMGB1 were elevated, especially in the patients with interstitial lung diseases, which is a major complication leading to fatal outcomes." (PMID 35013338, 2022). "Notably, serum calpain activity and HMGB1 levels in SSc patients with interstitial lung disease (ILD) were significantly higher than those in SSc patients without ILD." (PMID 32393322, 2020). "Importantly, the average HMGB1 level in PM/DM patients with interstitial lung disease (ILD) was 25.84 ng/ml, which is significantly higher than that in PM/DM patients without ILD [12.68 ng/ml] (p < 0.05)." (PMID 27537498, 2016). "Although the trigger for AE-IPF has not been sufficiently elucidated, these data suggest that higher levels of HMGB1 play a role in the development of lung injury superimposed with interstitial lung disease (ILD), including IPF." (PMID 33980944, 2021). "Patients with new-onset DM and PM have elevated serum HMGB1, and these levels correlate with survival and the presence of interstitial lung disease (ILD)." (PMID 32363191, 2020). "Although the role of HMGB1 in the pathogenesis of interstitial lung diseases has not been elucidated, inhibition of necroptosis might also be beneficial for interstitial lung diseases complicated with inflammatory myopathies." (PMID 35013338, 2022).
kidney injuries (6 papers, 2019 to 2025). "High doses of cisplatin in the antitumor setting primarily induce apoptosis and release HMGB1 extracellularly after injury to activate a sterile inflammatory response, as has been reported in some cisplatin-induced kidney injuries 39-41." (PMID 38169643, 2024). "Our data further suggest that HMGB1 plays a critical role in ORF3a-inflicted kidney injuries, as overproduction or downregulation of HMGB1 protein production resulted in corresponding changes in renal cellular KIM-1 response and cytokine production." (PMID 39345136, 2024). "The study also revealed that miR-129-5p alleviated acute kidney injury via targeting the HMGB1/TLRs/NF-κB pathway." (PMID 34326879, 2021). "In this study, HMGB1 translocation was observed in the context of TCE-induced kidney injury." (PMID 40842957, 2025).
lymphopenia (6 papers, 2013 to 2025). Reduction in the number of lymphocytes. "This study’s objective was to shed light on the changes in systemic immune cellular responses, cellular exhaustion/anergy and lymphopenia in PT rats by neutralizing the early systemic HMGB1 levels." (PMID 34209240, 2021). "Our pilot study showed that splenectomy attenuated lymphopenia in the blood, thus we further examined if this is related with less HMGB1 being released in the plasma." (PMID 23555048, 2013). "THS also elicited a robust inflammatory response, with significant elevations in circulating interleukin-6 and high mobility group box 1 (both: P < 0.001), neutrophilia ( P < 0.001), lymphopenia ( P < 0.001), and increased inflammatory gene expression across a number of tissues." (PMID 41185419, 2025). "When compared with the sham group, the number of total peripheral blood mononuclear cells (PBMCs) is significantly reduced while plasma HMGB1 levels increases, which suggests that HMGB1 may regulate lymphopenia and immunodepression." (PMID 31001089, 2019). "Furthermore, HMGB1-RAGE signaling is involved in functional exhaustion of mature monocytes and lymphopenia after ischemic injury, which is a hallmark of immunodepression after ischemia, thereby affecting the peripheral immune response." (PMID 29555931, 2018). "Furthermore, we showed that glycyrrhizin, as a HMGB1 inhibitor, which directly combines with HMGB1 and induces conformational changes, significantly attenuated lymphopenia." (PMID 23555048, 2013). "We investigated the hypothesis that T cells are required for the reductions in non-T cell subsets observed in SIID, and further examined a potential correlation between lymphopenia and High-mobility group protein B1 (HMGB1) release, a protein that regulates inflammation and immunodepression." (PMID 23555048, 2013). "All of these results confirmed the negative correlation between HMGB1 release and lymphopenia, suggesting that HMGB1 participates in the process of SIID." (PMID 31001089, 2019).
myositis (6 papers, 2013 to 2022). "In patients with myositis, HMGB1 presented with cytoplasmic and extracellular translocation in both endothelial cells and infiltrated immune cells." (PMID 35250993, 2022). "Treatment with a necroptosis inhibitor or anti-HMGB1 antibodies ameliorates myositis-induced muscle weakness as well as muscle cell death and inflammation in the muscles." (PMID 35013338, 2022). "IMNM (n = 62) and inclusion body myositis (IBM, n = 14) patients had increased sarcoplasmic HMGB1 compared with other myositis patients (n = 46)." (PMID 32363191, 2020). "Another well-characterized DAMP that is involved in myositis pathogenesis is high mobility group box protein 1 (HMGB1)." (PMID 23758833, 2013). "High expression of HMGB1 was detected not only in the cytoplasm of muscle, infiltrating cells and endothelial cells, but also in the interstitial space in myositis muscle suggesting its potential to engage TLRs in this milieu." (PMID 23758833, 2013). "The pro-inflammatory effect of HMGB1 in myositis was mainly mediated by TLR4." (PMID 35250993, 2022). "Aberrant HMGB1 expression occurs in myositis patients and correlates with weakness." (PMID 32363191, 2020). "In addition, immunomodulators such as fibrinogen and HMGB1 are correlated with the progression of myositis and are believed to induce autophagy by signaling through TLR-4, indicating a probable association with innate immune mechanisms." (PMID 23758833, 2013). "The interaction of HMGB1 with toll-like receptor 4 (TLR4) induces muscle weakness and fatigue in patients with myositis, while the binding of HMGB1 to the receptor for advanced glycation end-products (RAGE) decreases survival in muscle-wasting mouse models." (PMID 36497194, 2022). "Herein, we compare HMGB1 expression (serological and sarcoplasmic) in patients with IMNM with that of other myositis subtypes using immunohistochemistry and ELISA." (PMID 32363191, 2020). "Serum HMGB1 levels were elevated in patients with IMNM, dermatomyositis and polymositis, and those myositis patients with extramuscular inflammatory features." (PMID 32363191, 2020). "A recent study reported that HMGB1 induced muscle fatigue occurs via the TLR-4 pathway in muscle and that the HMGB1-TLR-4 pathway plays a role in the pathogenesis of myositis patients." (PMID 23758833, 2013). "Extracellular HMGB1 also promoted muscle fatigue through TLR4 in patients and mice with myositis." (PMID 35250993, 2022).